PALB2 (partner and localizer of BRCA2)
Diseases named in the same sentence as PALB2 in open-access papers (continued):
Sharing a sentence is not in itself a finding about the gene and the disease.
breast cancer (continued). "The detection rate was 4.35% (n=8) for actionable breast cancer PVs (ATM=2, PALB2=4, CHEK2=1, PTEN=1)." (PMID 33758026, 2022). "We designed a rapid, digital pathway, supported by a genetics specialist hotline, for delivery of germline testing of BRCA1/BRCA2/PALB2 (BRCA-testing), integrated into routine UK NHS breast cancer care." (PMID 35868849, 2022). "Breast cancer patients enrolled under the Malaysian Breast Cancer Genetic Study between October 2002 and February 2018 were tested for BRCA1, BRCA2 and PALB2 genes." (PMID 35167615, 2022). "From 12,182 abstracts, 15 studies measuring gene penetrance covering 5 putative male breast cancer genes were found: ATM, BRCA1, BRCA2, CHEK2, and PALB2." (PMID 35885460, 2022). "In summary, the Talazoparib Beyond BRCA trial is a prospective study that identifies the sensitivity of gPALB2 breast cancers to PARP inhibition and highlights the core role of PALB2 in BRCA1- and/or BRCA2-mediated HR DNA repair in human breast cancers." (PMID 36253484, 2022). "For breast cancer, several genes such as BRCA1, BRCA2, PALB2, ATM, and CHEK2 act as high- to moderate-penetrance cancer susceptibility genes." (PMID 35853889, 2022). "Most women with breast cancers had panel testing, allowing extrapolation of likely frequencies of other common familial genes (ATM, CHEK2, PALB2)." (PMID 34312777, 2021).
breast cancer (continued). "The odds ratios for breast cancer diagnosed at age 40 or below were 28.8 for BRCA1 (95% CI 18.6–44.5); 3.8 for CHEK2 (95% CI 2.5–5.5); and 3.6 for PALB2 (95% CI 1.6–7.5), and all were statistically significant." (PMID 32824581, 2020). "Susceptibility genes with high or moderate penetrance (i.e., BRCA1, BRCA2, PALB2, ATM, and CHEK2) have been identified in 30 to 40% of patients with a family history of breast cancer, but only in 5% of sporadic breast cancer cases." (PMID 33126731, 2020). "It is possible that members of the FA core complex that act upstream of HRR are less relevant for breast cancer due to their more specialized function in the repair of crosslinks while BRCA1, BRCA2, and PALB2 function more globally at DNA double-strand breaks." (PMID 31467304, 2019). "Estimates are that about 1.1–1.7% of women with breast cancer have a PV in CHEK2, 1.4–2.1% in BRCA1, 1.6–2.2% in BRCA2, 0.87–1% in ATM, and 0.84–0.87% in PALB2, with other genes less than 1%." (PMID 30832243, 2019). "The National Comprehensive Cancer Network (NCCN) guidelines for genetic assessment in hereditary breast cancer (version 3.2019) recommends genetic evaluation of ATM, CDH1, CHEK2, NBN, NF1, and PALB2 in addition to BRCA1/2 genes." (PMID 31658756, 2019). "Gene-panel testing of BRCA1, BRCA2, PALB2 and RNASEL in the Australian Breast Cancer Family Registry identified five carriers of RNASEL:p.Glu265* in 591 early onset breast cancer cases." (PMID 29422015, 2018). "Furthermore, Catucci and colleagues have also recently shown that the Lys939Trp variant does not disrupt the homologous recombination-mediated DNA repair activity of PALB2 and they concluded that this variant should be regarded as neutral with no clinical relevance to risk of breast cancer." (PMID 28279176, 2017). "However, prospective data related to the clinical outcomes of PALB2 mutation carriers is lacking and very little information (beyond mutation penetrance) is available to guide current clinical management for carriers (affected and unaffected by breast cancer)." (PMID 27099641, 2016). "This variant, first reported in a Swedish ovarian cancer patient with a family history of breast cancer and other malignancies, lies on the BRCA1 coiled-coil domain and was reported to disrupt the interaction between BRCA1 and PALB2." (PMID 24845084, 2014). "Breast cancer tumor suppressors BRCA1, BRCA2 and PALB2 form a complex and play key roles in homologous recombination (HR), DNA double strand break (DSB) repair and cell cycle regulation following DNA damage." (PMID 23585894, 2013). "Notably, of the 3 individuals with germline deleterious PALB2 mutations, 2 have moderate family history with Manchester score of 12 and 14 respectively, whereas one developed breast cancer at late age in the absence of any family history of cancer (Manchester score of 2)." (PMID 23977390, 2013). "PALB2 protein [OMIM #610355, a partner and localizer of BRCA2] was recently identified in a complex with BRCA2 (Breast Cancer 2) protein." (PMID 20122277, 2010). "In Australia, a PALB2 mutation has been found, c.3113G > A, carried by 5 (0.4%) of 1,403 unselected population-based patients diagnosed before age 60 years, 8 (1%) of 779 cases from families with multiple cases of breast cancer, and none of 764 unaffected population-based controls." (PMID 21182766, 2010).
breast cancer (continued). "At the pilot sites, PV/LPVs in breast cancer genes were most commonly identified in ATM, BRCA2, and BRCA1, whereas at the non-pilot sites, they were most commonly identified in BRCA2, BRCA1, and PALB2." (PMID 39292401, 2025). "This was largely driven by the increased incidence of TNBC which accounted for 56% of BRCA1 carriers with T1N0 breast cancer (90% of whom received chemotherapy), while only 15.6% of BRCA2 and 40% of PALB2 carriers had T1N0 TNBC (of which 80% and 100% received chemotherapy, respectively; eTable 1)." (PMID 40275390, 2025). "HRD extends beyond BRCA1/BRCA2 mutations to include non-BRCA genes (RAD51C/RAD51D, BRIP1, BARD1, ATM, PALB2), broadening actionable targets across ovarian and breast cancer subtypes, including HER2-positive (30–40%) and luminal subtypes (15–25%)." (PMID 40864792, 2025). "All breast cancer patients in the universal testing group underwent BRCA1, BRCA2 and PALB2 testing." (PMID 41568010, 2025). "Heritable breast cancer (BC) is influenced by well-known high-penetrance genes such as BRCA1, BRCA2, PALB2, and CHEK2, but the contribution of many moderate- and low-penetrance genes remains unclear." (PMID 41463216, 2025). "This individual had no documented family history of breast cancer, history of hormone treatments, BRCA1, BRCA2, PALB2 or CHEK2 P/LP variants or other explanation on chart review." (PMID 39802765, 2024). "Two recent large case control studies CARRIERS in the USA3 and BRIDGES mainly in Europe4 identified six additional genes with actionable increased risks of breast cancer with ORs of around twofold to threefold (RAD51C, RAD51D, BARD1, ATM, CHEK2) and one at fourfold to fivefold (PALB2)." (PMID 38609177, 2024). "Among patients with hereditary high-risk breast cancer, including early-onset breast cancer, familial breast cancer, bilateral breast cancer, triple-negative breast cancer (TNBC) and male breast cancer, PALB2 mutation rates are relatively high." (PMID 38914840, 2024). "Cumulative lifetime penetrance estimates for female breast cancer are taken from the literature review performed by the All Syndromes Known to Man Evaluator28–32: 0.35 (ATM), 0.73 (BRCA1), 0.72 (BRCA2), 0.19 (CHEK2), and 0.38 (PALB2)." (PMID 38760335, 2024). "In current study, all the PALB2 PVs/LPVs were identified in breast cancer cases and no PALB2 PVs or LPVs were found in ovarian cases." (PMID 37169825, 2023). "Pathogenic variants in high‐risk breast cancer predisposition genes (BRCA1, BRCA2, and PALB2) were found in 4.5% of older women with triple‐negative breast cancer." (PMID 36544278, 2023). "In this sub-group, age at breast cancer diagnosis was no longer a significant predictor of mutation status for ATM (OR 1.12, 95% CI 0.97–1.30) and PALB2 remained non-significant (OR 1.05, 95% CI 0.90–1.23)." (PMID 37084156, 2023).
breast cancer (continued). "Breast cancer 1 (BRCA1) and breast cancer 2 (BRCA2) play an important role in the HR repair pathway by interacting with other DNA repair proteins such as Fanconi anemia (FA) proteins, ATM, RAD51, PALB2, MRE11A, RAD50, and NBN." (PMID 35785170, 2022). "Using the breast cancer study as an example, it was found that the known eight famous genes—BRCA1, BRCA2, PALB2, BARD1, RAD51C, RAD51D, and ATM—in breast cancer research and practice actually lead to very low accuracy in predicting breast cancer status at the stage of diagnosis." (PMID 36298522, 2022). "Although PALB2 encodes a protein involved in DNA double-strand break repair carried out by BRCA2, tailored therapies for breast cancer patients carrying PVs in genes other than BRCA1/2 have not yet been established." (PMID 33718150, 2021). "In Poland, 20 founder mutations in BRCA1, BRCA2, CHEK2, PALB2, NBN, RECQL are responsible for the majority of hereditary breast cancer cases in women, but the utility this genes panel has not been tested in men." (PMID 34461861, 2021). "Moreover, based on the sequencing genomic DNA (from 1,370 cases and 1,635 controls), approximately 5.6% of patients are the carriers of a pathogenic variant in breast cancer gene 1 (BRCA1), BRCA2, partner and localizer of BRCA2 (PALB2), or tumor protein 53 which are the main penetrant genes of BC." (PMID 36046117, 2021). "Three more PALB2 germline PVs producing truncated protein were identified among 81 European FPC family, each of these three family had also history of breast cancer (none of the patients was carrier of BRCA2 mutation)." (PMID 33718150, 2021). "Importantly, genes related to breast cancer, such as ESR1 or PALB2 were observed in all the analyzed samples, before and after culture." (PMID 34071445, 2021). "The gene panel offered by GHSNZ since 2015 was not available when the PALB2 and PTEN variant carriers identified in this work presented with breast cancer." (PMID 33113089, 2021). "Using inherited breast cancer as an example, follow-up strategies to manage elevated breast cancer risks may include either enhanced breast cancer screening or bilateral mastectomy for high penetrance genes, such as BRCA1/2 and PALB2." (PMID 34645413, 2021). "Our findings that docetaxel alone or in combination is effective in TNBC PDXs from patients without gBRCA1/PALB2 mutations (by large, the most frequent subgroup of TNBC breast cancer) are coincident with other PDX literature studies." (PMID 33782404, 2021). "Recent studies from the United Kingdom and Australia have shown that multigene testing (BRCA1, BRCA2 and PALB2, and BRCA1 and BRCA2, respectively) for all breast cancer patients would be cost-effective when compared with current eligibility criteria based on personal and family-history testing." (PMID 33113089, 2021). "Mutations in PALB2/FANCN increase breast and pancreatic cancer incidence, while truncating variants of BRIP1/FANCJ and RAD51C/FANCO increase ovarian but not breast cancer." (PMID 32962238, 2020).
breast cancer (continued). "BRCA1 and BRCA2 germline pathogenic variants were found in 7.3% of the IBC patients, 6.3% had a mutation in other cancer genes (PALB2, CHEK2, ATM and BARD1), and 1.6% had a germline pathogenic variant in other genes not related with breast cancer." (PMID 32075053, 2020). "Two of the 16 PALB2-associated breast cancers subjected to WES, however, lacked both bi-allelic inactivation of PALB2 and genomic features of HRD." (PMID 31428676, 2019). "Despite PALB2 variants are rarely identified in 1–4% of BRCA negative families, but increasing evidence suggests its increased risk for breast cancer as compared to BRCA2 mutations." (PMID 30975222, 2019). "Indeed, inactivation of BRCA1, BRCA2, PALB2, FAM175A, and BARD1 are synthetic lethal with PARG depletion in MCF7 breast cancer cells due to disruption of HR-mediated DDR." (PMID 30889383, 2019). "Four of the 12 PALB2-breast cancers with bi-allelic PALB2 inactivation subjected to WES lacked a dominant signature 3, despite displaying high LST scores." (PMID 31428676, 2019). "It is therefore not surprising that we have found PALB2 pathogenic mutations in women with pure DCIS and that they are more common in women with a first-degree relative with breast cancer." (PMID 31060593, 2019). "Three genes with evidence for association with breast cancer are on the eMERGEseq platform (ATM, CHEK2, PALB2), but were not used to develop outcomes." (PMID 30011878, 2018). "PALB2 exons were amplified from 460 BRCA1/2-mutation negative women with familial breast and/or ovarian cancer and early-onset breast cancer using AmpliSeq technology and sequenced on an Ion Torrent PGM sequencer." (PMID 28279176, 2017). "Among these, rare monoallelic LoF variations within the PALB2 gene (partner and localiser of BRCA2) are associated with breast cancer at a risk two to four times that among non-mutation carriers." (PMID 28449691, 2017). "Of the non-BRCA genes, ATM, BRIP1, PALB2, PTEN and CHEK2, are reported to be medium-to-high penetrance genes that cause hereditary breast cancer." (PMID 26824983, 2016). "PALB2 c.196C>T has previously been reported to be carried by 2/972 (0.2%) and 1/70 (1.4%) familial breast cancer cases (and none in controls) in Australian and USA studies, respectively." (PMID 23448497, 2013). "Four PALB2 p.Q775X positive cases were also identified in a subsequent study involving 564 (0.7%) breast cancer cases not selected for family history of cancer, which also showed that 6% of cases harbored common BRCA1, BRCA2 or CHEK2 mutations." (PMID 23302520, 2013).